SNORA40 (small nucleolar RNA, H/ACA box 40)
Synonyms: ACA40; SNORA40A
Gene: Small nucleolar RNA gene on chromosome 11 (93,735,111 to 93,735,236, reverse strand). Ensembl gene ENSG00000210825.
Gene Ontology:
Biological process: RNA processing
Cellular component: nucleolus
Homologues: Orthologues: chimpanzee SNORA40 (99% identical), macaque SNORA40 (97% identical). Paralogues in human: SNORA40B (98% identical), SNORA40C (94% identical).
Diseases named in the same sentence as SNORA40 in open-access papers:
SNORA40 is named in the same sentence as 5 diseases in open-access papers, as found by Europe PMC text mining. Sharing a sentence is not in itself a finding about the gene and the disease. The quoted sentences say what the papers report.
asthma (1 paper, 2015). "All this evidence suggests that SNORA40 may have a consistent and relevant role in aberrant responses of the immune system such as allergic (asthma) and autoimmune (multiple sclerosis) responses." (PMID 25880556, 2015). "Besides, SNORA40, along with other snoRNAs and olfactory receptor genes, was found to be part of a coexpression module composed of genes upregulated in exacerbations of children with asthma." (PMID 25880556, 2015).
lung squamous cell carcinoma (1 paper, 2021). "The third example RES resides in SNORA40 at chr11:93,468,111 and demonstrated prognosis significance in lung squamous cell carcinoma (LUSC) (adjust p = 0.0159)." (PMID 34319007, 2021).
multiple myeloma (1 paper, 2015). "SNORA40 has been seen to be overexpressed in plasma cells (antibody-secreting B cells) from patients with multiple myeloma of the TC1 subgroup when compared to those from healthy controls." (PMID 25880556, 2015).
multiple sclerosis (1 paper, 2015). A progressive autoimmune disorder affecting the central nervous system resulting in demyelination. "Finally, the combination of differential expression and differential coexpression analyses has allowed the identification of miR-20b, miR-331-5p, miR-1246 and SNORA40 as potential theraputic targets in multiple sclerosis, SNORA40 being the promising candidate." (PMID 25880556, 2015).
cancer (1 paper, 2021). A tumor composed of atypical neoplastic, often pleomorphic cells that invade other tissues. "SNORA40 is a small nucleolar RNA and has been proposed as a biomarker for several cancer types." (PMID 34319007, 2021).